TTI1 (TELO2 interacting protein 1)
Description:
Regulator of the DNA damage response (DDR). Part of the TTT complex that is required to stabilize protein levels of the phosphatidylinositol 3-kinase-related protein kinase (PIKK) family proteins. The TTT complex is involved in the cellular resistance to DNA damage stresses, like ionizing radiation (IR), ultraviolet (UV) and mitomycin C (MMC). Together with the TTT complex and HSP90 may participate in the proper folding of newly synthesized PIKKs. Promotes assembly, stabilizes and maintains the activity of mTORC1 and mTORC2 complexes, which regulate cell growth and survival in response to nutrient and hormonal signals.
Synonyms: KIAA0406; smg-10; NEDMIM
Tractability: Small molecule: a structure with a bound ligand is known. PROTAC: UniProt records ubiquitination sites on it; ubiquitination databases record sites on it; its protein half-life has been measured.
Gene: Protein-coding gene on chromosome 20 (37,983,007 to 38,033,461, reverse strand). Ensembl gene ENSG00000101407.
Subcellular location: Cytoplasm
Subcellular location (Human Protein Atlas): Vesicles; Nucleoplasm
Gene Ontology:
Molecular function: kinase binding; protein binding; protein-containing complex stabilizing activity
Biological process: positive regulation of DNA damage checkpoint; protein stabilization; regulation of TOR signaling
Cellular component: cytoplasm; TORC1 complex; TORC2 complex; TTT Hsp90 cochaperone complex; nucleus
Genetic constraint (gnomAD): Loss-of-function variants: 55 observed, 88.27 expected, observed/expected ratio (o/e) 0.62, 90% interval 0.5 to 0.78. The upper end of that interval is the gene's LOEUF score, 0.78, which puts it in group 3 of 6, group 1 being the genes least tolerant of losing a copy. Missense variants: 1,173 observed, 1,333.1 expected, observed/expected ratio (o/e) 0.88, 90% interval 0.84 to 0.92. Synonymous variants: 512 observed, 520.64 expected, observed/expected ratio (o/e) 0.98, 90% interval 0.91 to 1.06.
Homologues: Orthologues: chimpanzee TTI1 (99% identical), macaque TTI1 (97% identical), rabbit TTI1 (88% identical), dog TTI1 (88% identical), pig TTI1 (87% identical), guinea pig TTI1 (86% identical), mouse Tti1 (85% identical), rat Tti1 (85% identical), zebrafish tti1 (53% identical), tropical clawed frog tti1 (45% identical), Drosophila melanogaster Tti1 (19% identical), Caenorhabditis elegans R10H10.7 (15% identical).
Diseases named in the same sentence as TTI1 in open-access papers:
TTI1 is named in the same sentence as 12 diseases in open-access papers, as found by Europe PMC text mining. Sharing a sentence is not in itself a finding about the gene and the disease. The quoted sentences say what the papers report.
colorectal cancer (2 papers, 2024 to 2026). A primary or metastatic malignant neoplasm that affects the colon or rectum. "Here we show that TELO2-interacting protein 1 (TTI1) is a direct transcriptional target of β-catenin/TCF in colorectal cancer." (PMID 42283915, 2026). "Targeting TTI1 is therefore a promising approach to improve chemotherapy efficacy in Wnt/β-catenin-activated colorectal cancer." (PMID 42283915, 2026). "Genetic depletion of TTI1 destabilizes ATM and ATR, attenuates DNA damage signaling, impairs double-strand break repair, and sensitizes colorectal cancer cells to 5-fluorouracil and oxaliplatin." (PMID 42283915, 2026).
multiple myeloma (2 papers, 2021 to 2024). "For instance, TTI1 has been shown to facilitate survival in multiple myeloma via the mTORC1 pathway." (PMID 38501918, 2024). "Aberrant expression of FBXO9 to regulate mammalian target of rapamycin signaling by targeting Tel2 and Tti1 degradation promotes survival of multiple myeloma cells." (PMID 34480022, 2021).
bladder cancer (1 paper, 2018). "TTI1, an HSP90 co-chaperone that helps fold phosphoinositide 3’-kinase-related kinases (PIKKs), was found to be overexpressed in 28% of bladder cancer cases." (PMID 30220976, 2018). "TTI1, RAF1 and YWHAZ combined are found to be overexpressed in 55% of all bladder cancer cases." (PMID 30220976, 2018). "No matter the mechanism though, the fact that TTI1 (28%) is overexpressed and kinase-PIK3Ca signaling (72%) is altered in a significant number of bladder cancer cases indicates that reducing the chaperone activity that supports this axis may be viable approach to treating MIBC." (PMID 30220976, 2018).
colonic adenomas (1 paper, 2026). "Pharmacological suppression of the TTT complex by piperlongumine mimics TTI1 loss and enhances the anti-tumor activity of chemotherapy in cell lines, xenografts, Apc-mutant patient-derived organoids and Apcmin/+ colonic adenomas." (PMID 42283915, 2026).
Intellectual disability (1 paper, 2023). "The importance of TELO2–TTI1–TTI2 (TTT) assembly is illustrated by its association with syndromic intellectual disability and You–Hoover–Fong syndrome, which are caused by mutations of TTI1 and TELO2, respectively." (PMID 37298208, 2023).
liver carcinoma (1 paper, 2024). An epithelial or non-epithelial malignant neoplasm that arises from the liver. "Nevertheless, the influence of TTI1 on the development of liver carcinoma is still not clear." (PMID 38501918, 2024).
metastasis (1 paper, 2020). The spread or migration of cancer cells from one part of the body (where they first appeared) to another. "Interestingly, in plasma DNA, the first detection of the TTI1 mutation was in a sample collected after adjuvant chemotherapy for treating primary tumor, and the second was after chemotherapy for treating lung metastasis, with VAFs of 2.6% and 4.2%, respectively." (PMID 32592321, 2020).
microcephaly (1 paper, 2019). A congenital or acquired developmental disorder in which the circumference of the head is smaller than normal for the person's age and sex. "In addition, TTI1, a candidate pathogenic gene, was identified in a family with microcephaly and ID where a homozygous missense mutation (c.G2761A, p.D921N) segregated with the phenotype in two affected and four unaffected family members." (PMID 31737043, 2019).
Primary microcephaly (1 paper, 2020). Head circumference below 2 standard deviations below the mean for age and gender at birth. "Genes associated with primary microcephaly were often differentially expressed during development, with highest expression during the early embryonic and fetal periods (ASPM, WDR62, MCPH1, STIL, KIF23 and TTI1)." (PMID 32182809, 2020).
cancer (8 papers, 2015 to 2024). A tumor composed of atypical neoplastic, often pleomorphic cells that invade other tissues. "Despite the generally low PSI values for the 325 cryptic 3’SSs from the CLL-only analysis, we identified four genes previously implicated in cancer (TTI1, MAP3K7, FXYD5, PFDN5) and six others (YIF1A, ORAI2, ZNF91, ZNF548, RP11–1280I22." (PMID 25768983, 2015). "Five cryptically spliced genes (ANKHD1, ATM, FOXP1, MAP3K7, and TTI1), identified in previous transcriptomic analyses in SF3B1-mutated patients, were analyzed in different cancer types." (PMID 33585229, 2020). "Therefore, we posit that ALKBH5, through its regulatory action on TTI1 expression, serves as a pivotal determinant in either promoting or inhibiting specific malignancy-associated cellular behaviors in HCC, underlining a sophisticated network of genetic interactions pivotal to cancer cell dynamics." (PMID 38501918, 2024).
tumor (6 papers, 2020 to 2026). "Multivariate linear regression analysis identified SNPs in 11 genes (Sepsecs, Rhobtb1, Tsen15, Abcc3, Arid5b, Tnr, Dock2, Tti1, Fam81a, Stx6, and Oxr1) that were independently associated with the tumour multiplicities." (PMID 39067134, 2024). "We pooled all 20 genes (Stx6, Ramp1, Traf3ip1, Nckap5, Pfkfb2, Trmt1l, Rprd1b, Rer1, Sepsecs, Rhobtb1, Tsen15, Abcc3, Arid5b, Tnr, Dock2, Tti1, Fam81a, Oxr1, Plxna2 and Tbc1d31) together as the mouse tumour susceptibility gene signature (mTSGS)." (PMID 39067134, 2024). "Interestingly, as depicted in the Polar chart, when considering the specific gene deregulation associated to drug sensitivity, CTNNBL1, RNF24 and TTI1 showed in primary HGSOC cell lines the same trend observed in tumor tissue from HGSOC patients." (PMID 35120576, 2022). "Cytotoxicity assays, combined with gene-expression analysis in primary HGSOC cell lines, allowed to define CTNNBL1, RNF24, and TTI1 as cell-autonomous contributors to tumor resistance." (PMID 35120576, 2022). "Multivariate analyses flagged SNPs in 20 genes (Stx6, Ramp1, Traf3ip1, Nckap5, Pfkfb2, Trmt1l, Rprd1b, Rer1, Sepsecs, Rhobtb1, Tsen15, Abcc3, Arid5b, Tnr, Dock2, Tti1, Fam81a, Oxr1, Plxna2, and Tbc1d31) independently tied to various tumour characteristics, designated as a mTSGS." (PMID 39067134, 2024). "Interestingly, we showed that CTNNBL1, RNF24 and TTI1 are associated to resistance to therapy in both primary HGSOC cell lines and patients’ samples, in line with available literature data on the role of these proteins as tumor cell-derived resistance factors." (PMID 35120576, 2022).
TTI1 also shares sentences with these, for which no sentence is quoted: leukemia (1 paper).